ADGRE5 (adhesion G protein-coupled receptor E5)
Description:
Receptor potentially involved in both adhesion and signaling processes early after leukocyte activation. Plays an essential role in leukocyte migration.
Synonyms: CD97; TM7LN1
Tractability: Antibody: UniProt places it where antibodies can reach, with high confidence; its Gene Ontology location is reachable by antibodies, with high confidence; UniProt predicts a signal peptide or a membrane-spanning region; the Human Protein Atlas places it where antibodies can reach. PROTAC: ubiquitination databases record sites on it.
Target class: Family B G protein-coupled receptor; Membrane receptor
Gene: Protein-coding gene on chromosome 19 (14,380,501 to 14,408,729, forward strand). Ensembl gene ENSG00000123146.
Subcellular location: Cell membrane; Secreted, extracellular space (Adhesion G protein-coupled receptor E5 subunit alpha)
Subcellular location (Human Protein Atlas): Plasma membrane; Golgi apparatus; Predicted to be secreted
Pathways (Reactome):
Immune System: Neutrophil degranulation
Signal Transduction: Class B/2 (Secretin family receptors)
Gene Ontology:
Molecular function: protein binding; G protein-coupled receptor activity; transmembrane signaling receptor activity; calcium ion binding
Biological process: cell adhesion; cell surface receptor signaling pathway; cell-cell signaling; G protein-coupled receptor signaling pathway; immune response; inflammatory response; immune system process
Cellular component: extracellular exosome; focal adhesion; membrane; plasma membrane; secretory granule membrane; extracellular region
Genetic constraint (gnomAD): Loss-of-function variants: 68 observed, 85.5 expected, observed/expected ratio (o/e) 0.8, 90% interval 0.65 to 0.97. The upper end of that interval is the gene's LOEUF score, 0.97, which puts it in group 4 of 6, group 1 being the genes least tolerant of losing a copy. Missense variants: 916 observed, 984.55 expected, observed/expected ratio (o/e) 0.93, 90% interval 0.88 to 0.98. Synonymous variants: 416 observed, 403.85 expected, observed/expected ratio (o/e) 1.03, 90% interval 0.95 to 1.12.
Homologues: Orthologues: chimpanzee ADGRE5 (97% identical), chimpanzee ADGRE5 (96% identical), macaque ADGRE5 (92% identical), dog ADGRE5 (68% identical), pig ADGRE5 (67% identical), guinea pig ADGRE5 (61% identical), mouse Adgre5 (57% identical), rat Adgre5 (57% identical), rabbit ADGRE5 (55% identical), zebrafish si:ch211-241f5.3 (22% identical). Paralogues in human: ADGRE2 (58% identical), ADGRE1 (28% identical), ADGRE3 (28% identical), ADGRL2 (28% identical), ADGRL3 (27% identical), ADGRL1 (26% identical), ADGRL4 (22% identical), ADGRB1 (20% identical), ADGRF5 (20% identical), ADGRB2 (20% identical), ADGRD1 (20% identical), ADGRB3 (18% identical), and 30 more.
Diseases named in the same sentence as ADGRE5 in open-access papers:
ADGRE5 is named in the same sentence as 39 diseases in open-access papers, as found by Europe PMC text mining. Sharing a sentence is not in itself a finding about the gene and the disease. The quoted sentences say what the papers report.
melanoma (4 papers, 2024 to 2025). A malignant, usually aggressive tumor composed of atypical, neoplastic melanocytes. "The LAMININ, FN1, ADGRE5, SPP1, MK, CDH1, and APP signals mainly originated from melanoma cells and were received by multiple cell types, suggesting that melanoma cells play extensive roles in the ecosystem." (PMID 41357561, 2025).
breast carcinoma (3 papers, 2018 to 2025). "Six of the genes (CASP1, CCL2, ADGRE5, IL3RA, RSPO1, and STAB1) are co‐expressed with the CH25H gene in both cancers, while two genes (ANPEP in breast cancer and CCL8 in prostate cancer) are exclusively co‐expressed with the CH25H gene in one of the tumors." (PMID 41159143, 2025). "It was found in our study that RBM47, PCBP3, FRG1, SRP72 and other RBPs may regulate the AS of ITGA6, ADGRE5, TNC and other genes and affect the EMT process of breast cancer cells." (PMID 38783078, 2024). "RBM47, PCBP3, FRG1, SRP72 and other RBPs might regulate AS of ITGA6, ADGRE5, TNC and other genes and affect the EMT process of breast cancer cells." (PMID 38783078, 2024). "For example, increased expression levels of ADGRG1, ADGRE5, and ADGRF5 has been detected in a variety of human cancers such as glioma (ADGRG1), gastric, pancreatic, esophageal, prostate, colorectal carcinomas (ADGRE5), and breast cancer (ADGRF5)." (PMID 29468160, 2018). "By establishing the correlation network of differential RBPs and differential AS events, we found that RBM47, PCBP3, FRG1, SRP72, RBMS3 and other RBPs may regulate the AS of ITGA6, ADGRE5, TNC, COL6A3 and other cell adhesion genes, which may affect the EMT process of breast cancer cells." (PMID 38783078, 2024).
colorectal carcinoma (3 papers, 2018 to 2022). A malignant epithelial neoplasm that arises from the colon or rectum and invades through the muscularis mucosa into the submucosa. "CD97/ADGRE5 is highly elevated in breast, thyroid, stomach, pancreatic, esophageal, and colorectal cancers, and has been linked to tumor metastasis through the β-catenin, PI3K/AKT, MAPK, and Rho-GEFE signaling pathways." (PMID 36551877, 2022). "Interestingly, differential expression of ADGRE5 has also been described for several solid cancers such as lung, thyroid and colorectal carcinomas, indicating a tumor and/or tissue-specific expression pattern." (PMID 30953469, 2019).
leukemia (3 papers, 2019 to 2022). A malignant (clonal) hematologic disorder, involving hematopoietic stem cells and characterized by the presence of primitive or atypical myeloid or lymphoid cells in the bone marrow and the blood. "By correlating these data to the relevant clinic-pathological parameters of the patients, CD97/ADGRE5 has been identified as a leukemia-associated candidate in acute myeloid (AML), (pediatric) acute lymphoblastic, and chronic lymphocytic leukemia." (PMID 35563846, 2022). "Overexpression of CD97, also known as adhesion G protein-coupled receptor E5 (ADGRE5), in the leukemia stem cells of AML patients is associated with a poor prognosis 23, which is in line with the results of the present study." (PMID 31528236, 2019). "An increased ADGRE5 expression is found in some types of leukemia." (PMID 30953469, 2019).
esophageal cancer (2 papers, 2021 to 2022). A primary or metastatic malignant neoplasm involving the esophagus. "The expression of CD97/ADGRE5, a member of the aGPCR family, was significantly upregulated in breast, thyroid, stomach, pancreas, esophageal cancer and CRC and was associated with the metastasis of a variety of tumors 17-19." (PMID 34421349, 2021). "Accordingly, ADGRE5 is one of the most highly-expressed aGPCR across all cancers; e.g., in thyroid, gastric, and esophageal carcinomas and melanoma." (PMID 35563846, 2022). "In a genome-wide methylation study of esophageal carcinomas, ADGRE5 was identified as one out of 23 (1/23) genes with relevance in tumor progression/metastasis." (PMID 35563846, 2022).
prostate carcinoma (2 papers, 2023 to 2025). A carcinoma that arises from epithelial cells of the prostate gland. "Several of the identified cell surface markers have known associations with prostate cancer and metastasis including CD59, 4F2 cell-surface antigen heavy chain (SLC3A2) and adhesion G protein-coupled receptor E5 (CD97)." (PMID 38053024, 2023).
co-infection (1 paper, 2025). "In parallel, ADGRE5-ALCAM-related co-stimulatory and adhesion interactions showed pair-specific dynamics: CD6-ALCAM and ITGAV-ITGB1-ADGRE5 were most prominent in the HIV-mono group and diminished with Mtb co-infection, whereas CD55-ADGRE5 did not display a comparable monotonic trend." (PMID 41394852, 2025).
diabetic nephropathy (1 paper, 2018). "Increased expression levels were found for ADGRL2, ADGRL4, ADGRE1, ADGRE5, ADGRG2, and ADGRG6 in lupus nephritis and diabetic nephropathy, whereby ADGRL2, ADGRL4 and ADGRE5 were also upregulated in IgA nephropathy." (PMID 29468160, 2018).
hepatocellular carcinoma (1 paper, 2022). A malignant tumor that arises from hepatocytes. "For example, although ADGRE5 is the most-mutated aGPCR gene in hepatocellular carcinoma, mutations only occur in 2% of cases." (PMID 35563846, 2022).
IgA nephropathy (1 paper, 2018). "A role of these genes in vascular and/or inflammation-mediated kidney diseases is further substantiated by the associations with diabetes nephritis (ADGRE1, ADGRE5), lupus nephritis (ADGRE1, ADGRE2, ADGRE5), renal vasculitis (ADGRE2, ADGRE5), IgA nephropathy (ADGRE5) and renal hypertension (ADGRE5)." (PMID 29468160, 2018).
lung squamous cell carcinoma (1 paper, 2024). "Higher levels of ADGRE5 were associated with worse prognosis in both lung squamous cell carcinoma and LIHC." (PMID 38913193, 2024).
lymph node metastasis (1 paper, 2025). "Three genes—ADGRE5, COTL1, and LCP1—were significantly upregulated in OSCCs with lymph node metastasis compared to those without lymphatic metastasis." (PMID 41044643, 2025).
lymphoma (1 paper, 2019). A malignant (clonal) proliferation of B- lymphocytes or T- lymphocytes which involves the lymph nodes, bone marrow and/or extranodal sites. "To determine ADGRE5 isotype distribution in aggressive lymphoma, we performed Western blot analyses and found that the short isoform (EGF1,2,5) is homogeneously expressed in all cell lines, while the largest isoform (EGF1,2,3,4,5) was preferentially present in BL cell lines." (PMID 30953469, 2019).
osteoarthritis (1 paper, 2025). A noninflammatory degenerative joint disease occurring chiefly in older persons, characterized by degeneration of the articular cartilage, hypertrophy of bone at the margins and changes in the synovial membrane. "suggests that inflammatory macrophages in osteoarthritis are extensively affected by ADGRE5 activation of their own SPI1 to regulate of inflammation, phagocytosis, and cell signaling." (PMID 40181977, 2025).
osteoporosis (1 paper, 2022). A condition of reduced bone mass, with decreased cortical thickness and a decrease in the number and size of the trabeculae of cancellous bone (but normal chemical composition), resulting in increased fracture incidence. "If these findings are confirmed, VAV3 and ADGRE5 might turn out to be novel therapeutic targets for the treatment of osteoporosis." (PMID 35434450, 2022). "Combined, these mouse and human data highlight VAV3 and ADGRE5 as novel putative high‐BMD genes with additive effects, and potential therapeutic targets for osteoporosis." (PMID 35434450, 2022).
osteosarcoma (1 paper, 2025). A usually aggressive malignant bone-forming mesenchymal neoplasm, predominantly affecting adolescents and young adults. "In TAMs, LPAR6 expression was positively correlated with ADGRE5, IL10, and IL6, which was further validated in the osteosarcoma cohort." (PMID 41502512, 2025). "Next, we investigated the correlation between LPAR6, ADGRE5, IL10, and IL6 in scRNA-seq and the TARGET osteosarcoma cohort." (PMID 41502512, 2025).
preeclampsia (1 paper, 2023). Preeclampsia is a hypertensive disorder of pregnancy that is characterized by new-onset hypertension with proteinuria presenting after 20 weeks of gestation, and depending on mild or severe forms may initially present with severe headache, visual disturbances, and hyperreflexia. "ADGRE5 promoted trophoblast invasion via the PI3K/Akt/mTOR signaling pathway, which was decreased in preeclampsia patients." (PMID 37501789, 2023).
rheumatoid arthritis (1 paper, 2025). A chronic, systemic autoimmune disorder characterized by inflammation in the synovial membranes and articular surfaces. "Previous studies have found elevated expression of soluble ADGRE5 in the synovial fluid of patients with rheumatoid arthritis." (PMID 39935605, 2025). "This highlights the catalytic role of ADGRE5 in rheumatoid arthritis development." (PMID 39935605, 2025).
thyroid cancer (1 paper, 2022). "Consistently, transgenic Adgre5 increased the frequency of pERK- and Ki67-positive tumor cells in a thyroid cancer model." (PMID 35563846, 2022).
viral infections (1 paper, 2025). "A four-gene blood signature that includes ISG15, IL16, 2′,5′-Oligoadenylate Synthetase Like (OASL), and Adhesion G protein-coupled Receptor E5 (ADGRE5) yielded an AUC of over 0.90 in distinguishing various viral infections from non-viral conditions." (PMID 39861921, 2025).
tumor (17 papers, 2018 to 2025). "ADGRE5 has been implicated in favoring localized tumor growth, enhancing cellular migration, and promoting metastatic spread across various cancer types." (PMID 40862763, 2025). "Multiple studies have shown that ADGRE5 is an overexpressed tumor antigen in several cancer types and is associated with tumor migration, invasion, and metastasis." (PMID 39935605, 2025). "Neutrophils are recipients to ADGRE5 signaling, which has a role in tumor invasion and metastasis, potentially reflecting tumor–neutrophil interactions." (PMID 38358352, 2024). "Further, we inferred cell–cell interactions, and observed that interactions of the ADGRE5 signaling pathway, which is associated with metastasis, were increased in MFTC compared to other tumor sub-populations." (PMID 36499343, 2022). "Upregulation of ADGRE5 is often observed at the invading tumor front as well as in advanced tumor stages." (PMID 30953469, 2019). "Depending on the cell type and tumor grade, ADGRE5 protein exists in three isoforms resulting from alternative splicing." (PMID 30953469, 2019). "In addition to its role in tumor cells, ADGRE5 is also postulated to have a role in immuno-oncology." (PMID 40862763, 2025). "ADGRE5 is a direct target of the tumor suppressor miR-126, often downregulated in tumors." (PMID 35563846, 2022). "Indeed, the inferred cell–cell communication network of the ADGRE5 signaling pathway showed that the interaction strength was highest in MFTC among the tumor sub-populations and second highest in TransMTC." (PMID 36499343, 2022). "The majority of tumor cell lines (Cancer Cell Line Encyclopedia, broadinstitute.org; accessed on 15 February 2022) have moderate to high ADGRE5 levels, indicating comparable ADGRE5 levels in the parental tumors." (PMID 35563846, 2022). "Since ADGRE5 plays an important role in tumor cell formation, metastasis and invasion, it might also be instrumental to better understand the different pathobiology of BL and DLBCL and help to explain discrepant clinical characteristics of BL and DLBCL." (PMID 30953469, 2019). "ADGRE5 was closely related with tumor cell adhesion, migration, angiogenesis, and apoptosis." (PMID 31464612, 2019). "However, various aGPCRs have been associated with cancer development and progression including GPR133/ADGRD1, which is required for glioblastoma growth; GPR116/ADGRF5, which furthers breast cancer metastasis; and CD97/ADGRE5 seems to enhance tumor cell invasion in several human malignancies." (PMID 29594040, 2018). "Studies have demonstrated that ADGRE5 and its ligand CD55 are co-expressed in cells of several tumor types." (PMID 40862763, 2025). "Taking advantage of the 3D hydrogel-based tumor-immune cell coculture system (3D-HYGTIC) constructed by us, we demonstrated that the PD-1-triggered increase in ADGRE5 expression was dependent upon IL32, which was suppressed by a STAT5 inhibitor." (PMID 38343549, 2024). "Despite being a well-defined participant in APC-CD4+ T-cell interactions, in-depth research on the role of ADGRE5 in tumor immunology is lacking." (PMID 38343549, 2024).
cancer (12 papers, 2018 to 2025). A tumor composed of atypical neoplastic, often pleomorphic cells that invade other tissues. "The expression level of ADGRE5 was strongly associated with EMT in various types of cancer." (PMID 38913193, 2024). "Studies indicate that ADGRE5 and CD55 are involved in different stages of cancer development, highlighting the potential of ADGRE5 as a therapeutic target in oncology/immuno-oncology." (PMID 40862763, 2025). "In cancer, ADGRE5 and CD55 are co-expressed and upregulated in several tumors, with higher expression often correlated to increased disease severity and poor prognosis." (PMID 40862763, 2025). "Regarding the key interaction between T cells and cancer cells, increased expression of ligand-receptor pairs MIF_TNFRSF10D, CD55_ADGRE5, CD226_NECTIN2, CCL3L1_CCR1, and CCL3_CCR1 was observed." (PMID 39986271, 2025). "Third, predicted interaction between CD55 expressed by CAFs, basal cancer cells and monocyte/macrophages and the adhesion G protein-coupled receptor E5 (CD97) gene, ADGRE5, on CD4+ T cells was higher with age." (PMID 41188599, 2025). "Among the interaction partners proposed for ADGRE5, CD55 stands out as an immune system component that is dysregulated in many cancers alongside ADGRE5." (PMID 40862763, 2025). "CD97/ADGRE5 is induced or noticeably upregulated in many cancers, whereas the corresponding normal tissue-specific cells have little or no ADGRE5." (PMID 35563846, 2022). "Detailed in vitro and in vivo analyses further indicated that ADGRG1 is a prosurvival factor in cancer cells and promotes anchorage-independent growth whereas ADGRE5 and ADGRF5 regulate RhoA-dependent cell migration and invasion." (PMID 29468160, 2018). "We performed a Pearson correlation analysis of ADGRE5, CD55 and IL32 in the pan-cancer TCGA database." (PMID 38343549, 2024). "In this cohort, CD55 expressed by CAFs, basal cancer cells, and monocyte/macrophages was predicted to interact with CD97 (ADGRE5) on CD4+ T cells, which promotes Treg development." (PMID 39483921, 2024). "LA-TAMs also participated in the modification of cancer cells by SPP1, VEGFA, RETN, GRN, ADGRE5, and HBEGF secretion." (PMID 37649596, 2023). "After verification of the STAT5-ADGRE5 axis of survT in independent ICIs cohorts, an ADGRE5-centered Tsurv model was then developed through ML for identification of MPR patients pre-ICIs and post-ICIs, both in TME and PBMCs, which was further verified in pan-cancer immunotherapy cohorts." (PMID 38343549, 2024). "Although datasetA and datasetB were baseline nonmetastatic cancers that had not undergone ICI therapy, we still observed obvious similarities in spatial distribution patterns across ADGRE5, IL32 and STAT5A/B." (PMID 38343549, 2024).
ADGRE5 also shares sentences with these, for which no sentence is quoted: infection (2 papers); Bacterial Infections (1); Burkitt lymphoma (1); chronic lymphocytic leukemia (1); congenital heart defects (1); COVID-19 (1); diffuse large B-cell lymphoma (1); endometriosis (1); glioblastoma (1); glioma (1); kidney diseases (1); lupus nephritis (1); male infertility (1); metastasis (1); neurodevelopmental disorder (1); renal hypertension (1); vitiligo (1).